SLC6A6 (solute carrier family 6 member 6)
Diseases named in the same sentence as SLC6A6 in open-access papers (continued):
Sharing a sentence is not in itself a finding about the gene and the disease.
breast carcinoma (1 paper, 2026). "Our prognostic analysis revealed that for SLC6A6, high expression is associated with poor prognosis in most breast cancer subtypes like total, luminal B subtype and basal subtype." (PMID 41597281, 2026). "Clinical analyses demonstrate that high Slc6a6 expression is strongly associated with poor prognosis in breast cancer patients, underscoring its relevance in human cancer progression beyond preclinical models." (PMID 41597281, 2026). "Taken together, these findings suggest that regulation of Slc6a6 is associated with Rprd1b level in breast cancer." (PMID 41597281, 2026). "Consistently, bioinformatics analysis based on the TCGA database and GEO datasets GSE1456 from UALCAN database revealed a significant upregulation of SLC6A6 in breast cancer tissues as compared to that in the matched normal tissues." (PMID 41597281, 2026). "These clinical data solidify SLC6A6-mediated Taurine transport as a driver of breast cancer malignancy and highlight its superior prognostic utility." (PMID 41597281, 2026). "Clinically, bioinformatics analyses correlate high SLC6A6 expression with poor prognosis in breast cancer patients, underscoring its potential as a therapeutic target." (PMID 41597281, 2026). "In this study, we identified the Taurine transporter Slc6a6 as a molecular determinant involved in breast cancer progression." (PMID 41597281, 2026). "Together, these findings suggested a potential link between elevated Slc6a6 and breast cancer." (PMID 41597281, 2026). "Moreover, we further evaluated the role of Slc6a6 in promoting breast cancer progression in vivo by injecting Slc6a6-OE cells into FVB mice." (PMID 41597281, 2026). "Furthermore, bioinformatics analysis of clinical datasets revealed that high SLC6A6 expression correlates with poor prognosis in certain subtype breast cancer patients." (PMID 41597281, 2026). "Together, these data reveal the clinical involvement of SLC6A6 in breast cancer." (PMID 41597281, 2026). "Together, these data suggest Slc6a6 maybe serve as an oncogene in breast cancer progression." (PMID 41597281, 2026). "However, comprehensive analyses of SLC6A6 expression and its relationship with survival have not been performed in breast cancer." (PMID 41597281, 2026).
breast tumors (1 paper, 2026). "Additionally, we observed a significant positive correlation between SLC6A6 and RPRD1B mRNA levels in breast tumors (R = 0.22, p = 5.7 × 10−13)." (PMID 41597281, 2026).
cataract (1 paper, 2024). Partial or complete opacity of the crystalline lens of one or both eyes that decreases visual acuity and eventually results in blindness. "To validate the snRNAseq of human limbus biopsies from cataract patients, we performed immunohistochemistry, immunocytochemistry, and cell purification for in vitro clonogenicity assays using the limbal progenitor markers SLC6A6 and ITGβ4 identified through snRNAseq." (PMID 38514716, 2024).
colorectal adenocarcinoma (1 paper, 2021). The most common type of colorectal carcinoma. "Slc6a6 is also associated with colorectal adenocarcinomas, which could impact nutrient absorbance and overall fish health." (PMID 34421633, 2021).
early-onset retinal dystrophy (1 paper, 2026). "This cohort study evaluates the association between variants in SLC6A6 and hereditary early-onset retinal dystrophy." (PMID 41343195, 2026).
enteritis (1 paper, 2015). Inflammation of the small intestine. "In Atlantic salmon (Salmo salar), slc6a6 was shown by microarray to be significantly up-regulated in distal intestine during the early response (day 3) to a soybean meal containing diet, and therefore, potentially associated with the development of soybean meal induced enteritis." (PMID 26610852, 2015).
hypotaurinemic retinal degeneration and cardiomyopathy (1 paper, 2025). "The variant also mapped to SLC6A6, a taurine and beta-alanine transporter gene, implicated in Hypotaurinemic Retinal Degeneration and Cardiomyopathy (HTRDC) and kidney fibrosis in diabetic knockout mice." (PMID 39974050, 2025).
ischemic stroke (1 paper, 2024). A stroke disorder caused by obstruction of blood flow to the brain, due to thrombotic (local blood clot formation) or embolic (due to a blood clot or other material traveling from another site) event. "While both Slco4a1 and Slc6a6 are known targets of NFAT5, the latter may in fact influence the outcome of ischemic stroke by regulating the transport of the neuroprotective endogenous amino acid taurine through the BBB." (PMID 39710754, 2024).
Leber congenital amaurosis (1 paper, 2026). Leber congenital amaurosis (LCA) is a retinal dystrophy defined by blindness and responses to electrophysiological stimulation (Ganzfeld electroretinogram (ERG)) below threshold, associated with severe visual impairment within the first year of life. "Genetic, clinical, and functional outcomes of pathogenic variants in SLC6A6 in individuals with Leber congenital amaurosis (LCA) and EORD." (PMID 41343195, 2026).
lung carcinoma (1 paper, 2026). "Immunofluorescence staining images show that in the A549 lung cancer cell line, SLC6A6 is mainly distributed in the cell membrane, with expression also observed in the cytoplasm." (PMID 41597281, 2026).
migraine (1 paper, 2024). "A few ion channel markers, such as Kccn3 (potassium Calcium-Activated Channel Subfamily N Member 3) and Slc6a6 (sodium and chloride-ion dependent transporter) overlapped between mTBI, CSD and IS, where Kcnn3 has been associated with migraine pathology." (PMID 39578726, 2024).
myeloid leukaemia (1 paper, 2025). "Collectively, our data identify a critical requirement for SLC6A6 expression in primary human AML growth and indicate that blocking taurine transport may be of value in aggressive myeloid leukaemias." (PMID 40369079, 2025).
myopia (1 paper, 2021). "Therefore, the increased level of SLC6A6 may prompt myopia by using GABA as a substrate." (PMID 33946922, 2021). "SLC6A6 has never been previously reported as involved in myopia pathways." (PMID 33946922, 2021).
osteosarcoma (1 paper, 2026). A usually aggressive malignant bone-forming mesenchymal neoplasm, predominantly affecting adolescents and young adults. "In contrast, in the U2OS osteosarcoma cell line, SLC6A6 is localized within the nucleus." (PMID 41597281, 2026).
retinal disease (1 paper, 2026). "In conclusion, this study investigated 4 unrelated families with autosomal recessive LCA/EORD associated with biallelic pathogenic variants in the SLC6A6 gene, extending observations on single pedigrees from previous reports and confirming the association between SLC6A6/TauT and retinal disease." (PMID 41343195, 2026).
retinoblastoma (1 paper, 2015). A malignant tumor that originates in the nuclear layer of the retina. "The mechanisms regulating taurine levels in retinoblastoma are unclear but may involve either regulation of its synthesis from the precursor hypotaurine and/or regulation of uptake from the extracellular environment, mediated by the taurine transporter SLC6A6." (PMID 26348444, 2015).
steatosis (1 paper, 2021). Increased lipid within the cytoplasm of cells. "Of note, the summed expression of SLC6A6 and SLC6A8 was positively associated with IHTG %, suggesting that their expression increases with steatosis (p = 0.04)." (PMID 34192533, 2021).
tuberculosis (1 paper, 2012). A chronic, recurrent infection caused by the bacterium Mycobacterium tuberculosis. "A genomic region on BTA 22 was suggestively associated with tuberculosis susceptibility; it contains the taurine transporter gene SLC6A6, or TauT, which is known to function in the immune system but has not previously been investigated for its role in tuberculosis infection." (PMID 22355315, 2012).
tumor (27 papers, 2017 to 2026). "Our study revealed that elevated serum Taurine levels and concomitant upregulation of its transporter, Slc6a6, are associated with enhanced tumor growth." (PMID 41597281, 2026). "However, in the context of tumor metabolic reprogramming and core oncogenic mutations, taurine assumes unique roles in the tumor microenvironment.Tumor cells overexpress SLC6A6 to uptake taurine, leading to reduced taurine levels in CD8+ T cells." (PMID 40630945, 2025). "Functionally, Slc6a6 overexpression drives tumor progression in vivo and accelerates cancer cell proliferation in vitro." (PMID 41597281, 2026). "Consistently, SLC6A6 or RPRD1B is predominantly overexpressed in tumor tissues compared to normal tissues, suggesting its oncogene potential in most cancers." (PMID 41597281, 2026). "Due to tumor heterogeneity, we adopted the PyMT tumor model, which better recapitulates tumor initiation and progression, to investigate the function of Slc6a6." (PMID 41597281, 2026). "The results demonstrated that Slc6a6-OE significantly increased tumor weight compared to the control group." (PMID 41597281, 2026). "Quantitative PCR analysis of mammary tissues from normal mice and tumor tissues from tumor-bearing mice confirmed higher Slc6a6 expression in the latter group." (PMID 41597281, 2026). "First, we observed that tumor-bearing mice exhibited elevated serum Taurine levels alongside increased expression of the Taurine transporter Slc6a6." (PMID 41597281, 2026). "Among the distinctively upregulated genes in low EGF treatment, we found genes related to anti-tumor immunity, sperm flagellar assembly, and mitogenesis (SLC6A6, DNAH17, DUOX1)." (PMID 39694501, 2025). "Tumor cells outcompete CD8+ T cells for taurine by overexpressing SLC6A6, which consequently induces endoplasmic reticulum (ER) stress in CD8+ T cells through a PERK‐ATF4‐dependent mechanism." (PMID 40223597, 2025). "Recent studies have revealed that tumor cells promote progression by overexpressing the Tau transporter SLC6A6 to compete with CD8+ T cells for Tau, leading to T cell exhaustion and dysfunction; supplementation with Tau reverses this process." (PMID 40826133, 2025). "Tumor cells, by overexpressing SLC6A6, outcompete CD8+ T cells for TAU, leading to T cell death and dysfunction, which in turn drives tumor progression." (PMID 39339648, 2024). "SLC6A6-facilitated TAU uptake supports the malignant behavior of tumor cells while also promoting the survival and function of CD8+ T cells since TAU is the most abundant free amino acid in the leukocyte’s cytoplasm." (PMID 39339648, 2024). "From the Human Protein Alts (HPA) database, we observed higher SLC6A6 protein levels in tumor tissues compared to normal mammary gland tissues, suggesting that SLC6A6 may be upregulated in tumors." (PMID 41597281, 2026). "Furthermore, we discovered that Slc6a6 interacts with Rprd1b, a protein known to promote tumor progression, thus linking two proteins that were previously considered unrelated." (PMID 41597281, 2026). "To explore this further, firstly, we utilized bioinformatics databases to identify potential interacting partners of SLC6A6, but did not identify any proteins with known or potential associations with tumorigenesis or tumor progression." (PMID 41597281, 2026). "Given that Taurine is transported by Slc6a6 in mice, we investigated whether Slc6a6 expression is upregulated in tumor-bearing mice." (PMID 41597281, 2026). "Therefore, we investigated whether Slc6a6 could also be expressed in the nucleus of PyMT tumor cells under TNF-α stimulated conditions." (PMID 41597281, 2026). "Therefore, we hypothesized that the interaction between Slc6a6 and Rprd1b might promote cell cycle progression, thereby enhancing cell proliferation and tumor growth." (PMID 41597281, 2026).
tumor (continued). "Overall, the function of SLC6A6/TAUT in tumors is complex and context-dependent, and more research is needed to fully understand its role in tumor biology and its potential as a therapeutic target." (PMID 41597281, 2026). "Cancer cells can outcompete CD8 + T cells for taurine by overexpressing the taurine transporter SLC6A6, leading to taurine depletion in T cells, which induces cell death and dysfunction, thereby promoting tumor progression." (PMID 41582215, 2026). "We found that SLC6A6 and SLC6A8 had higher expression levels in liver metastases than in normal pancreatic tissues and primary tumours." (PMID 37370109, 2023). "On the other hand, SLC6A6 and SLC22A4 are transporters, SART3 is a tumor rejection antigen, VPS41 is involved in organelle development, SEMA4C is involved in axon guidance, and SHMT1 is an enzyme with involvement in glycine, serine, and threonine metabolism." (PMID 30973896, 2019). "In this work, we focus on the transporters for taurine (TauT, SLC6A6) and creatine (CT-1, SLC6A8) as they could play important roles in tumour growth and development." (PMID 36835201, 2023). "The genes SLC6A6 and FAP, that are up-regulated in the High-stroma/CMS4 subtype, show in-silico interaction with miR-30b which is down-regulated in tumors and in the stroma versus the epithelia component of the tumor." (PMID 36358609, 2022).
cancer (17 papers, 2017 to 2026). A tumor composed of atypical neoplastic, often pleomorphic cells that invade other tissues. "Functional studies further validate its oncogenic role: Slc6a6 overexpression enhances Taurine uptake, conferring a proliferative advantage and reducing apoptosis in cancer cells." (PMID 41597281, 2026). "Cells take up NCT via the taurine transporter SLC6A6, which, as we’ve seen, is often upregulated in cancer cells." (PMID 39789296, 2025). "In previous publications, SLC6A6 expression has been shown to drive tumorigenesis and affects clinical outcomes in cancer." (PMID 38535903, 2024). "On the other hand, overexpression and increased activity of SLC6A6 or SLC6A8 proteins were described in several types of cancer." (PMID 36835201, 2023). "Based on immunochemistry data, it was also noticed that the intensity of SLC6A6 staining with anti-SLC6A6 antibodies was mostly stronger in cancer tissue in comparison to the normal cells." (PMID 36835201, 2023). "The four genes selected through our process which are dysregulated along with CLDN1 and CLDN7 (PIK3CA, SLC6A6, ASAP1, and TMEM-43) are implicated in a variety of cancers." (PMID 34571860, 2021). "This may be the primary reason why cancer cells overexpress the taurine transporter SLC6A6, because taurine can assure the high pH in the matrix that promotes β-oxidation of fatty acids." (PMID 39789296, 2025). "It was tested how SLC6A6 signalling could influence the side population (SP) cells and their cancer stem cell (CSC)-like properties." (PMID 36835201, 2023). "Genetic knockdown of Slc6a6 significantly suppressed cell proliferation, whereas its overexpression enhanced Taurine uptake, leading to decreased apoptosis and increased proliferation in cancer cells with enhancing the progression of the G1/S transition of cell cycle." (PMID 41597281, 2026). "Herein, we present the potential role of taurine (SLC6A6) and creatine (SLC6A8) transporters in cancer development as well as therapeutic potential of their inhibitors." (PMID 36835201, 2023). "We discuss the potential of SLC6A6 and SLC6A8 transporters as the targets in therapy of cancers and analyze the features important for development of their new ligands as well." (PMID 36835201, 2023). "At this moment, finding potent inhibitors of SLC6A6 and SLC6A8, which may be tested in cancer cell lines, seems to be a challenge for scientists." (PMID 36835201, 2023). "With respect to the genes having interaction(s) with miRNAs, we realized four down-regulated vDEGs (TMEM100, MYH11, CHRDL1, and FAM107A) to the accompaniment of five up-regulated vDEGs (KLK10, CLDN1, SLC6A6, MMP11, and SLC7A5) being documented by the GEPIA in both COAD and READ cancer types." (PMID 35333898, 2022). "Collectively, these findings suggest that PIK3CA and SLC6A6 may promote the development of chemoresistance, in part through the regulation of EMT and cancer stemness." (PMID 34571860, 2021).
infection (5 papers, 2021 to 2025). The state of being infected such as from the introduction of a foreign agent such as serum, vaccine, antigenic substance or organism. "RCAN1, SLC6A6, RHOB, DUSP, TGM3, and TP53INP2 DEGs, which are related to DNA damage-induced apoptosis, autophagy, the cell cycle, and inflammatory repression, were also upregulated after vPdR-36U infection." (PMID 40006915, 2025).
retinopathy (4 papers, 2016 to 2026). "In family 4, trio genome sequencing identified the cause of the proband’s severe retinopathy by detecting a homozygous pathogenic truncating variant—NM_003043.6: c.338G>A, p.(Trp113Ter)—in the SLC6A6 gene, with parents being heterozygous carriers (eFigure 2D in Supplement 1)." (PMID 41343195, 2026).
inflammatory myopathy (2 papers, 2018 to 2024). "Confirming our earlier descriptive myopathological results on SLC5A3, SLC6A6, and AKR1B1 expression, we found these factors upregulated in regenerating muscle fibers present in biopsies in this new cohort of inflammatory myopathy patients." (PMID 30364257, 2018).
metabolic disease (1 paper, 2025). A congenital disorder (due to inherited enzyme abnormality) or acquired (due to failure of a metabolically important organ) disorder resulting from an abnormal metabolic process. "Specifically, the expression of SLC6A6, which facilitates taurine uptake, has been shown to be downregulated under certain conditions, such as oxidative stress or chronic inflammation, which are common in aging and metabolic diseases." (PMID 40458841, 2025).
SLC6A6 also shares sentences with these, for which no sentence is quoted: diabetic nephropathy (3 papers); liver fibrosis (3); acute kidney injury (2); diabetic cardiomyopathy (2); diabetic retinopathy (2); glioblastoma (2); Hyperglycemia (2); ischemic heart disease (2); liver disease (2); type 1 diabetes (2); acute myeloid leukemia (1); Anxiety (1); arteriosclerosis (1); Brugada syndrome (1); central nervous system disorder (1); chronic hepatitis (1); Cohen syndrome (1); colitis (1); cutaneous melanoma (1); cyst (1); depression (1); dystrophinopathy (1); end-stage renal disease (1); endothelial dysfunction (1); fibrosis (1); fracture (1); glioma (1); homocystinuria (1); Hyperinsulinemia (1); hypertrophy (1).
A further 24 diseases each share a sentence with SLC6A6 in 1 paper.